PRDM10 (PR/SET domain 10)
Description:
Transcriptional activator, essential for early embryonic development and survival of embryonic stem cells (ESCs) (By similarity). Supports cell growth and survival during early development by transcriptionally activating the expression of the translation initiation factor EIF3B, to sustain global translation (By similarity). Activates the transcription of FLNC.
Synonyms: KIAA1231; PFM7; TRIS; MGC131802; BHD2
Tractability: PROTAC: UniProt records ubiquitination sites on it; ubiquitination databases record sites on it; its protein half-life has been measured.
Target class: Enzyme; Transferase
Gene: Protein-coding gene on chromosome 11 (129,899,706 to 130,002,853, reverse strand). Ensembl gene ENSG00000170325.
Subcellular location: Nucleus
Subcellular location (Human Protein Atlas): Nucleoplasm; Nucleoli fibrillar center; Vesicles
Gene Ontology:
Molecular function: DNA-binding transcription factor activity; protein binding; transcription cis-regulatory region binding
Biological process: positive regulation of DNA-templated transcription; positive regulation of transcription by RNA polymerase II
Cellular component: chromatin; nucleoplasm; nucleus; transcription repressor complex
Genetic constraint (gnomAD): Loss-of-function variants: 59 observed, 124.65 expected, observed/expected ratio (o/e) 0.47, 90% interval 0.38 to 0.59. The upper end of that interval is the gene's LOEUF score, 0.59, which puts it in group 2 of 6, group 1 being the genes least tolerant of losing a copy. Missense variants: 1,098 observed, 1,497.2 expected, observed/expected ratio (o/e) 0.73, 90% interval 0.7 to 0.77. Synonymous variants: 556 observed, 579.9 expected, observed/expected ratio (o/e) 0.96, 90% interval 0.89 to 1.03.
Homologues: Orthologues: chimpanzee PRDM10 (99% identical), macaque PRDM10 (99% identical), rat Prdm10 (94% identical), rabbit PRDM10 (94% identical), pig PRDM10 (93% identical), mouse Prdm10 (92% identical), dog PRDM10 (88% identical), guinea pig PRDM10 (83% identical), tropical clawed frog prdm10 (74% identical), zebrafish prdm10 (66% identical). Paralogues in human: ZNF410 (10% identical), ZNF76 (9% identical), PRDM1 (9% identical), MTF1 (9% identical), ZNF451 (9% identical), ZNF281 (8% identical), PATZ1 (8% identical), VEZF1 (8% identical), HIC1 (8% identical), ZNF143 (8% identical), ZBTB16 (7% identical), ZNF384 (7% identical), and 24 more.
Diseases named in the same sentence as PRDM10 in open-access papers:
PRDM10 is named in the same sentence as 28 diseases in open-access papers, as found by Europe PMC text mining. Sharing a sentence is not in itself a finding about the gene and the disease. The quoted sentences say what the papers report.
breast carcinoma (2 papers, 2015 to 2019). "It has been reported that breast cancer cells show upregulated expression of PRDM10 associated with hypomethylation of the PRDM10 gene, suggesting the involvement of this gene in the proliferation and invasion of breast cancer cells." (PMID 30872976, 2019). "We found that copy number amp/gain of NSD1 or PRDM1, or loss of SETDB2 or PRDM10 was significantly associated (p<0.05) with shorter survival in breast cancer patients." (PMID 25537518, 2015).
lipoma (2 papers, 2023 to 2024). A benign, usually painless, well-circumscribed lipomatous tumor composed of adipose tissue. "In conclusion, we identified a distinguishable syndrome partly overlapping with BHD, consisting of multiple lipomas, FF and RCC, caused by a missense variant in PRDM10." (PMID 36440963, 2023). "Recently, two independent reports have described the detection of missense variants at the same residue of PRDM10 gene (c.2029T > C (p.Cys677Arg) and c.2030G > A (p.Cys677Tyr)) in two families with a BHD-like phenotype (including fibrofolliculomas, trichodiscomas, lipomas, lung cyst(s), and RCC)." (PMID 38802529, 2024).
lipomatosis (2 papers, 2023 to 2025). A neoplastic process characterized by diffuse overgrowth of mature adipose tissue. "The lipomatosis could be either a direct effect of the PRDM10 variant, for example by gene expression changes other than FLCN reduction, or it may be an adipose tissue-specific effect of folliculin repression and downstream TFE3/TFEB activation, which is described to play a role in adipose tissue." (PMID 36440963, 2023). "A related novel hereditary disorder was linked to PR/SET domain 10 (PRDM10), which predisposes families to skin and mucosal lesions, lipomatosis and renal cell carcinomas." (PMID 40133475, 2025). "Our observations can serve as the basis for further functional studies into the roles of PRDM10 as a disease gene, and provide further insight into BHD, lipomatosis and RCC pathogenesis." (PMID 36440963, 2023).
lung carcinoma (2 papers, 2019 to 2023). "Consistently, we found borderline positive correlation between Bcl-2 and PRDM10 expression in breast, colon, and lung cancers." (PMID 31143550, 2019).
renal carcinoma (2 papers, 2024). A carcinoma arising from the epithelium of the renal parenchyma or the renal pelvis. "In addition, there are two recent reports of cases with cutaneous FF and renal cancer that were associated with rare missense variants in PRDM10 (p.Cys677Tyr and p.Cys677Arg)." (PMID 39085584, 2024).
sarcoma (2 papers, 2023 to 2025). A usually aggressive malignant neoplasm of the soft tissue or bone. "PRDM10 gene fusions with either MED12 or CITED2 have been reported in a small proportion of undifferentiated pleomorphic sarcomas." (PMID 36440963, 2023). "In our study, we aimed to detect PRDM10 gene rearrangement in superficial CD34-positive fibroblastic tumors and other pleomorphic sarcomas included in its differential diagnosis by immunohistochemistry and Fluorescence in situ hybridization." (PMID 40560238, 2025). "In conclusion, we suggested that PRDM10 gene rearrangement is not limited to superficial CD34-positive fibroblastic tumors; undifferentiated pleomorphic sarcomas may exhibit this molecular alteration and immunohistochemistry has lower sensitivity than fluorescence in situ hybridization." (PMID 40560238, 2025).
undifferentiated pleomorphic sarcoma (2 papers, 2020). An undifferentiated soft tissue sarcoma characterized by the presence of a pleomorphic malignant cellular infiltrate. "There were few reports in the past about PRDM10, and it had not been specially described in any other neoplasm but for undifferentiated pleomorphic sarcoma." (PMID 33119597, 2020).
Anxiety (1 paper, 2025). Intense feelings of nervousness, tension, or panic often arise in response to interpersonal stresses. "For PRDM10 rs74345126, the G allele has been associated with increased risks of anxiety and severe depression." (PMID 40002435, 2025).
colorectal cancer (1 paper, 2017). A primary or metastatic malignant neoplasm that affects the colon or rectum.
coronary artery disease (1 paper, 2012). "We observed genome-wide significant evidence of association of coronary artery disease with rare variants in the gene PRDM10 (P = 4.9 × 10–8)." (PMID 22951892, 2012). "We identified association of coronary artery disease with accumulations of minor alleles at rare variants in PRDM10 at genome-wide significance." (PMID 22951892, 2012).
gastric cancer (1 paper, 2018). A primary or metastatic malignant neoplasm involving the stomach.
liver cancer (1 paper, 2023). An epithelial or non-epithelial malignant neoplasm that arises from the liver. "Furthermore, PRDM10 is overexpressed in breast, colon and liver cancer samples." (PMID 36440963, 2023).
prostate carcinoma (1 paper, 2019). A carcinoma that arises from epithelial cells of the prostate gland. "PRDM10 has previously been found overexpressed in breast, ovary, kidney, colon, lung and prostate cancers." (PMID 31143550, 2019).
cancer (7 papers, 2018 to 2024). A tumor composed of atypical neoplastic, often pleomorphic cells that invade other tissues. "PRDM10 and PRDM13 have been implicated in both vertebrate development and cancer, but their expression profiles and function are less well-characterized relative to other members of the PRDM family." (PMID 33809237, 2021). "While both PRDM10 and PRDM13 have been implicated in key developmental processes, such as cell fate specification, and in various cancer, they remain significantly less well-characterized compared to their counterparts in the PRDM family." (PMID 33809237, 2021). "Using The Cancer Genome Atlas (TCGA) data set, we found weak positive correlation between PRDM10 and Bcl-2 in several cancer types including cancers of the breast, colon, and lung tissues." (PMID 31143550, 2019). "Importantly, our results showed correlation of Bcl-2 and PRDM10 expression in cancers overexpressing PRDM10." (PMID 31143550, 2019). "PRDM10 protein has been found overexpressed in certain cancers and hence may be expected to have oncogene like activities." (PMID 31143550, 2019). "As Bcl-2 is often over expressed in cancers, we next studied The Cancer Genome Atlas (TCGA) to see if Bcl-2 and PRDM10 expression may be correlated." (PMID 31143550, 2019). "We performed a candidate gene approach to search for cancer genes that might be regulated by PRDM10." (PMID 31143550, 2019). "Future studies will be required to determine whether siRNA targeting PRDM10 may serve as novel cancer therapy agents by inhibiting Bcl-2 expression." (PMID 31143550, 2019). "Similarly, PRDM10 was overexpressed at significant levels in breast (p < 0.001) and colon (p < 0.05) cancer specimens." (PMID 30347759, 2018). "Also, there is some evidence for a role of somatic aberrations of PRDM10 in cancer." (PMID 36440963, 2023). "Therefore, up-regulation of Bcl-2 by PRDM10 may be a potential mechanism for tumoriginesis in cancers overexpressing PRDM10." (PMID 31143550, 2019). "The results here suggest that PRDM10 may also play an oncogenic role in cancer." (PMID 31143550, 2019). "Intriguingly, we found that the protein expression levels of MECOM, PRDM5, PRDM10, and PRDM11 were generally higher in UCEC tissue compared to normal tissue, while the expression of PRDM1 was diminished in cancer tissue." (PMID 39468462, 2024). "Despite the pleiotropic roles of PRDM10 and PRDM13 in both development and pathological states such as cancer, little is known about their expression profiles." (PMID 33809237, 2021). "Consistent with the overexpression of PRDM10 and PRDM13 in numerous cancer types, both proteins were expressed in a wide spectrum of tissues in the developing embryo, supporting the need for future studies to probe their functional roles beyond what has been previously reported in the literature." (PMID 33809237, 2021). "A potential role for PRDM10 in cancer is to be highly expected since several better studied members of the PRDM family, PRDM2, PRDM3, PRDM5, and PRDM14, are known to play an important role in a variety of cancers." (PMID 31143550, 2019).
tumor (5 papers, 2017 to 2025). "The results showed that two cases diagnosed as superficial CD34-positive fibroblastic tumor and two cases diagnosed as undifferentiated pleomorphic sarcoma have PRDM10 gene rearrangement." (PMID 40560238, 2025). "Whether PRDM10 functions as a more canonical tumor suppressor gene, requiring functional inactivation of the second allele for development of neoplasms, is not clear yet." (PMID 36440963, 2023). "PRDM10 may serve as a transcriptional regulator for normal tissue differentiation and play important roles in promoting tumour development." (PMID 30872976, 2019). "Similarly, we found that hypomethylation of PRDM10 in PCa led to high expression in PCa samples, which may affect antitumour activity during tumour development." (PMID 30872976, 2019). "TCGA dataset mining was performed using UALCAN to shown that abnormal expression of the hub genes, including CDK1, VEGFA, PRDM10, RUNX1, CDK6, HSP90AA1, and MYC, were significantly up-regulated between ESCA primary tumor and normal tissues." (PMID 32662828, 2020). "In conclusion, our study suggests that AKT1, PRDM10, and FASN may be tumour promoters and that FLNA may be a tumour suppressor in PCa." (PMID 30872976, 2019).
PRDM10 also shares sentences with these, for which no sentence is quoted: chronic gastritis (1 paper); colon adenocarcinoma (1); depression (1); esophageal cancer (1); Fibrofolliculoma (1); follicular thyroid carcinoma (1); infection (1); nasopharyngeal carcinoma (1); rectum cancers (1); renal cell carcinoma (1); soft tissue tumors (1); type 1 diabetes (1); viral infection (1).